DNMT1 (DNA methyltransferase 1)
Diseases named in the same sentence as DNMT1 in open-access papers (continued):
Sharing a sentence is not in itself a finding about the gene and the disease.
cancer (continued). "Thus, it appears that even transient knockdown of UNC5A leads to robust/permanent activation of BCL2, which is similar to previously reported stable activation of cancer germline genes upon transient knockdown of DNA methyltransferase 1 (DNMT1)." (PMID 29720215, 2018). "In previous studies, the over-expressions of DNMT1 have been reported in the human cancers." (PMID 29721170, 2018). "Because of the crucial role of PDPK1 downstream PI3‐K/Akt pathway in cancer growth and progression 21, 40 and the reported links of the Akt in regulation of SP1 and DNMT1 expressions in several cancer types in other studies 33, 38, 41, we then assessed the role of Akt signalling in this process." (PMID 28840963, 2018). "The examined molecules include major class I and II histone deacetylases (HDACs), histone demethylases LSD1, JMJD2A and JMJD2D, histone methyltransferases EZH1, EZH2 and G9a, and DNA methyltransferase DNMT1, most of which have been shown to be deregulated in cancer cells." (PMID 29464084, 2018). "Moreover, a close cooperation between DNMT1 and DNMT3s was reported for the methylation of specific genes in cancer cells." (PMID 29449903, 2018). "We propose that TQ curbs cancer cell growth through dysfunction of DNA methyltransferase 1 (DNMT1)." (PMID 28415607, 2017). "In addition, overexpressions of DNMT1 and EZH2 were associated with induced proliferation and aggressive metastasis behavior, resulting in poor prognosis in many cancer types." (PMID 28360411, 2017). "However, there are only limited data showing that DNMT1 can be targeted with such compounds for the prevention or treatment of cancer." (PMID 29088821, 2017). "Furthermore, previous studies demonstrate the role of SP1 as a transcription factor of DNMT1 gene in several human cancer cells and mouse NIH3T3 cells." (PMID 29163762, 2017). "Although 5-Aza is shown in vitro and in vivo to inhibit DNMT1 and enhance therapeutic response in many cancers, caution should be exercised as genome-wide inhibition of DNA methylation might activate certain oncogenes." (PMID 28926997, 2017). "Since aberrant DNA methyltransferases (Dnmts) activity has been reported in numerous cancers, we examined the expression of the 3 major Dnmts: Dnmt1, Dnmt3a and Dnmt3b which are known to be involved in DNA methylation maintenance (Dnmt1) or de novo methylation (Dnmt3a and Dnmt3b)." (PMID 29073177, 2017). "Future profiling of acetyl-STAT3 and DNMT1 status in human cancers may provide an alternative therapeutic opportunity with a distinct mechanism of targeting the STAT3-DNMT1 interaction." (PMID 29137356, 2017). "Interestingly, prior data suggested that cancer related microRNAs can promote aberrant DNA methylation in tumors via targeting DNMT1." (PMID 28427182, 2017). "Expressions of DNMT3s are high in embryos where they set up a methylation pattern, they decrease over cell differentiation and development, and their expressions become deregulated in cancer where for example DNMT1 and 3B work in concert to establish aberrant DNA methylation." (PMID 28587163, 2017). "Interestingly, DBCCR1 attenuates the expression of DNMT1 (DNA methyltransferase 1), suggesting a reciprocal regulation between genetic silencing of cancer suppressor genes and activating DNA methylation." (PMID 28427182, 2017). "Furthermore, STAT3 acetylation but not tyrosine phosphorylation has been shown to be required to silence expression of many tumor suppressor genes such as SHP-1, CDKN2A by recruiting DNMT1 to methylate their promoter in cancer cells." (PMID 29126425, 2017). "In addition, stability of DNMT1 was increased in human cancers and DNMT1 is degraded by ubiquitin-dependent proteasomal degradation." (PMID 29137356, 2017).
cancer (continued). "Additionally, in cancer we and others observed that aberrant expression of DNMT1, DNMT3A, DNMT3B and histone deacetylases (HDAC) is involved in the inactivation process of RASSF1A." (PMID 29039788, 2017). "The methyl donor S-Adenosylmethionin (SAM) and the expression of DNA methyltransferase 1 (Dnmt1) are also impaired due to oxidative stress and may promote health disorders: for example, in cancer, an increased expression has been mentioned." (PMID 28613268, 2017). "Overexpression of DNMT1 has been detected in several kinds of human cancers." (PMID 29221215, 2017). "Most of these studies related to DNMT1 expression were performed using cancer cells." (PMID 28380423, 2017). "Since both acetylation of STAT3 and the level of DNMT1 are known to be elevated in a broad range of human cancers, it is likely that the STAT3-DNMT1 complex may participate the repression of TS genes by DNA methylation in various cancers." (PMID 29137356, 2017). "In addition to miRNAs, expression of DNMT1 which is an important epigenetic player involved in many processes including cancer, is seen to be altered." (PMID 28233878, 2017). "DNMT1, the maintenance methyltransferase, is widely expressed, particularly in the brain, where there is high expression, and is frequently upregulated in various human cancers such as colon, endometrioid, and prostate." (PMID 28764788, 2017). "In addition, DNMT1 was more expressed in poorly differentiated carcinoma than in well or moderately differentiated carcinoma (p = 0.01)." (PMID 29221215, 2017). "Additionally, inhibition of DNMT1 or elimination of Rad51 has been shown to sensitize cancer cells to chemotherapeutic agents." (PMID 27525019, 2016). "Elevation of DNMT1 and inactivation of pRb are two ubiquitous features of cancer cells." (PMID 27525019, 2016). "Therefore, curcumin exerts its anti-cancer function by downregulating DNMT1, thereby upregulating TCF21." (PMID 27894084, 2016). "So, RNAi-mediated depletion of DNMT1, which results in CpG island demethylation and re-expression of tumor suppressor genes, may be a strategy for cancer therapy." (PMID 27286455, 2016). "Moreover, DNMT1 inhibition has been shown to radiosensitize cancer cells by suppressing DNA DSB repair activity." (PMID 27525019, 2016). "The study showed that a repression complex Snail-G9a- DNA methyltransferase 1 may repress fructose-1,6-biphosphatase expression to change cellular metabolism and to increase cancer stem cell characters." (PMID 27531902, 2016). "Overexpression of DNMT1 has been shown in several cancers including lung." (PMID 27421653, 2016). "In addition to suppressing cancer cell proliferation, DNMT1 inhibition also sensitizes cancer cells to radiation." (PMID 27525019, 2016). "Given the role of DNMT1 in cancer progression and prognosis, we hypothesized that SNPs of DNMT1 may have prognostic value of cancer." (PMID 27087738, 2016). "Previous studies established that G2/M phase arrest and DNMT1 inhibition could sensitize cancer cells to radiation." (PMID 27525019, 2016). "This suggests that the DNMT1-inhibitory effect of THL is not specific to MCF-7 cells and that THL may be applied to reduce the viability of cancer cells with misregulated DNMT1 in general." (PMID 27525019, 2016). "As DNMT1 is the most abundant methyltransferase in dividing cells and occurs at lower levels in nondividing cells, it has become the major target for methylation inhibition in rapidly dividing cancer cells." (PMID 27525019, 2016). "In the same context, we have shown that the natural anti-cancer drug, epigallocatechin-3-gallate (EGCG) induces a significant decrease in UHRF1 and DNMT1 expression in Jurkat cells in association with p16INK4A upregulation, cell cycle G1/S arrest and apoptosis." (PMID 27839516, 2016).
cancer (continued). "In addition, Dnmt1 was shown to have cancer-specific de novo activity in a mouse model of MYC-induced T cell lymphomas, whereas Dnmt3a and Dnmt3b were primarily involved in maintenance methylation in tumors." (PMID 27690235, 2016). "As shown in this report, THL is herbal mixture that profoundly downregulated DNMT1 of cancer cells." (PMID 27525019, 2016). "In addition, expression of DNMT1 and EZH2 were associated with induced proliferation and aggressive metastasis behavior of cancer cells resulting in poor prognosis." (PMID 27421653, 2016). "However, there are recent reports that DNMT1 works together with DNMT3b in silencing genes in human cancer cells." (PMID 27317771, 2016). "Thus, re-expression of methylation-silenced tumor suppressor genes through inhibition of DNMT1 has emerged as an effective therapeutic strategy for cancer." (PMID 26362062, 2015). "Also noteworthy, miR-342-3p can inhibit cancer cell proliferation and invasion by targeting DNA methyltransferase 1 (DNMT1), a gene that maintains DNA methylation." (PMID 25607660, 2015). "Understanding these mechanisms might help to improve the application of DNMT1 inhibitors in the induction of silenced tumor suppressor genes during treatment of various cancers." (PMID 26032981, 2015). "Interestingly, two recent studies showed that depleting either DNMT1 or DNMT3B in cancer cells protects them from gene misregulation and cell cycle arrest induced by a DAC treatment, hence supporting our present findings." (PMID 25948775, 2015). "Study demonstrated that DNA methylation was one of an early step in cancer development and increased DNMT1 expression could be considered as a critical step in the oncogenic transformation of lung epithelial cells." (PMID 25598321, 2015). "The disruption of EZH2 and DNMT1 influenced tumorgenesis and cancer progression." (PMID 26362062, 2015). "The nuclear counterpart represented by the growing list of nuclear genes implicated in mitochondrial biology is equally crucial for understanding the complexities of cancer and neurodegeneration, now fuelled by the existence of an ideal model to investigate, the DNMT1-related human diseases." (PMID 25815005, 2015). "Targeting DNMT1 has become a promising strategy to prevent cancer occurrence." (PMID 25918249, 2015). "DNMT1 overexpression was identified in various cancers and it could result in epigenetic alteration of multiple tumor suppressor genes and ultimately lead to tumorigenesis and poor prognosis." (PMID 26571024, 2015). "In conclusion, δEF1 may associate with DNMT1, as well as MBD2 and 3, to establish and/or maintain methylation patterns in the E-cadherin promoter region in cancer cells." (PMID 25315069, 2015). "mir-29a, mir-148a, and mir-152 modulate Dnmt1 in cancer cells." (PMID 26261994, 2015). "Furthermore, the silence of DNMT1 expression in the A549/DDP cells reversed miR-148b-induced increases sensitivity of the drug-resistant cancer cells to cisplatin." (PMID 25927928, 2015). "Collective data suggest that JAHA, by down-regulating phospho-ERK, impairs DNMT1 and 3b expression and ultimately DNA methylation extent, which may be related to its cytotoxic effect on this cancer cytotype." (PMID 28793617, 2015). "Thus, re-expression of methylation silenced tumour suppressors via inhibition of DNMT1 has emerged as a potential therapeutic strategy against cancer." (PMID 25598321, 2015). "Similar to previous studies which have demonstrated that E-cadherin expression is regulated by DNMT1 in cancer, our results of ChIP assays showed that DNMT1 could directly bind to E-cadherin promoter region." (PMID 25863539, 2015).
cancer (continued). "Also in cancer cell lines, IL-6 is able to affect both the expression and nuclear translocation of DNA methyltransferase 1 (DNMT1), consequently changing its activity within the cell, and potentially targeting methylation to specific gene promoter regions." (PMID 25691854, 2014). "Although, many of the key gene-silencing events occur very early during the premalignant stages of tumor progression, the process of epigenetic gene silencing continues through the entire progression of human cancer, where DNMT1 plays the predominant role as the maintenance methyltransferase." (PMID 25478034, 2014). "There is considerable evidence indicating an up-regulation of DNMT1 in cancer." (PMID 24822169, 2014). "DNMT1 controls precise duplication and maintains the pre-existing global DNA methylation patterns after duplication in addition to gene-specific methylation in human cancer cells and DNMT3a/b are involved in de novo methylation." (PMID 25340937, 2014). "Knowing the rate of DNMT1 enzyme overexpression in human cancers, particularly in cases of hyper-methylated might be useful as part of the diagnostic and prognostic evaluation in human cancers." (PMID 25107489, 2014). "Therefore, inactivation of DNMT1 seems to be a valuable target for the development of cancer therapies." (PMID 24676085, 2014). "In addition, DNMT1 is necessary and sufficient to maintain global methylation and aberrant CpG island methylation in human cancer cells." (PMID 24987964, 2014). "To summarize, it appears that our data associate the disruption of the DNMT1/PCNA interaction with the presence of a global DNA hypomethylation phenotype, the acquisition of several cancer phenotypes, the hypomethylation of certain genes and with the presence of chromosomal aberrations." (PMID 24637615, 2014). "One study with prostate cancers demonstrated that the activity of DNMT1, DNMT3a, and DNMT3b are twofold to threefold higher in cancer cell lines and cancer tissues, as compared with a benign prostate epithelium cell line and benign prostatic hyperplasia tissues." (PMID 24822169, 2014). "Thus, 5-aza-CdR can effectively degrade DNMT1 to exert its anti-cancer effect against both AID-positive and AID-negative cells." (PMID 24457556, 2014). "To date, alterations within the DNMT1 gene have not been reported to be associated with cancer in the Caucasian population." (PMID 23638630, 2013). "Our data suggest that the DNMT1/DMAP1 interaction could be an effective anti-cancer target and opens a new avenue for the development of new strategies to design DNMT inhibitors." (PMID 23809695, 2013). "SAT2 is the target of DNA methyltransferase 1 (DNMT1) and an epigenetic modifier, whose methylation status may serve as a marker for cancer prognosis." (PMID 23423481, 2013). "As compared to normal CD138+ cells,PCs from MM and PCL patients showed higher expression of DNMT3A, and, at a lesser extent, of DNMT3B mRNAs, suggesting a potential role of de novo DNMTs in malignanttransformation; conversely, DNMT1 levels were lower in cancer cells compared to normal PCs." (PMID 23100393, 2012). "DNMT1 is the most abundant DNA methyltransferase in mammalian cells and the key maintenance enzyme for hemimethylated DNA during DNA replication of various cancer cells." (PMID 22295098, 2012). "However, smoking has been shown in other cancer types to activate DNA methyltransferase 1 (DNMT1) which catalyzes DNA methylation." (PMID 22645611, 2012). "The decrease of DNMT1 may play an important role in THL-induced apoptosis of NB4 cells as it is reported that depletion of DNMT1 could induce or promote apoptosis of cancer cells." (PMID 19897545, 2011). "Altogether, these observations show that immediately after DNA replication which generates hemi-methylated strands, UHRF1 is recruited with DNMT1 and/or likely DNMT3a and DNMT3b, in order to perpetuate gene repression, and particularly that of TSGs in cancer cells." (PMID 21496237, 2011).
cancer (continued). "How to down-regulate DNMT1 appears as a sound approach for epigenetic cancer therapies." (PMID 19897545, 2011). "This differential dependence on DNMT1 in maintaining cancer cell gene promoter hypermethylation and gene silencing may involve cooperativity between DNMTs." (PMID 21629434, 2010). "DNMT1 is thought to be responsible for most of the abnormal promoter methylation in cancer cells." (PMID 21629434, 2010). "The aberrant CpG methylation patterns in human cancer cells are inscribed by the de novo DNA cytosine-5 methyltransferases (DNMTs), DNMT3a and DNMT3b, and transmitted in the subsequent cell generations by the maintenance DNMT1." (PMID 21629434, 2010). "Overexpression of DNMT1 has been detected in several human cancers." (PMID 20969773, 2010). "The suppression of DNMT1 by an asON results in the demethylation of the p16 gene promoter, the reestablishment of its activity, the accumulation of cells with a hypomethylated retinoblastoma gene, and the inhibition of cancer cell proliferation." (PMID 22649602, 2009). "DNMT3b germline mutation are responsible for the immunodeficiency centromeric instability-facial anomalies (ICF) syndrome, the cancer risk of which is not known, while no DNMT1 germline mutation in any genetic syndrome has so far been reported." (PMID 16404435, 2006). "The expression level of DNMT1 showed an inverse correlation with that of miR-34a-5p, while it exhibited a positive correlation with the level of FoxM1, and high DNMT1 levels, low miR-34a-5p levels, and high FoxM1 levels were correlated with cancer recurrence in the HCC patients." (PMID 40050970, 2025). "Furthermore, expanding this line of research to other cancer types may help determine whether DNMT1 exerts similar regulatory roles in promoting metastasis and whether RASSF1A methylation status serves as a generalizable biomarker." (PMID 41381440, 2025). "Based on our results showing that CM-272 had an antiproliferative effect on NSCLC cells and altered the cell cycle, and that some epigenetic drugs can act as cancer drug sensitizers we wondered whether G9a/DNMT1 blockade would synergize with other cancer drugs." (PMID 39488528, 2024). "In conclusion, DNMT1 might be a promising target for cancer immunotherapy." (PMID 38279895, 2024). "However, whether DNMT1-mediated METTL16 expression is also observed in other cancer types warrants further investigation." (PMID 38334797, 2024). "Thus, we demonstrate that co-targeting G9a/DNMT1 is a promising strategy to enhance the efficacy of cancer drugs, and SCARA5 methylation could serve as a non-invasive biomarker to monitor tumor progression." (PMID 39488528, 2024). "In addition, we have also found that ICA-CUR could affect cancer cell development and the level of PD-L1 by targeting the DNMT1/IGFBP2 axis, which in turn influences the differentiation of immune T cells." (PMID 38778379, 2024). "However, the significant DNA hypomethylation observed in cancer cells following DNMT1 knockdown seems to contradict the prevailing notion that DNA hypomethylation may be linked to cancer initiation." (PMID 38755637, 2024). "Based on these studies, we speculate that the combination of ICA and CUR directly targets the DNMT1/IGFBP2 axis to affect cancer cell development and the level of PD-L1 to influence the differentiation of immune T cells, thereby affecting cancer cell development." (PMID 38778379, 2024). "Suppression of DNMT1 could result in the upregulation of the immune checkpoint proteins human leukocyte antigen G and indoleamine 2,3‐dioxygenase, which provided targets for cancer immunotherapy." (PMID 38279895, 2024). "Hence, the inhibition of DNMT1 has become a novel approach to cure cancer." (PMID 39595939, 2024). "Additionally, we found the expression of DNMT1 was increased in cancer specimens in three datasets." (PMID 36824133, 2023).